HK2 (hexokinase 2)
Diseases named in the same sentence as HK2 in open-access papers (continued):
Sharing a sentence is not in itself a finding about the gene and the disease.
tumor (continued). "It is therefore of paramount importance to finely dissect HK2 regulation, subcellular distribution and biochemical functions in tumor models, with the ultimate goal of identifying a selective and efficient mode of targeting it." (PMID 33946854, 2021). "Concurrently, we also assessed the expression of HK2 and c-Myc in the tumor tissues using western blots or immunohistochemical analysis." (PMID 33718248, 2021). "Overall, our work develops a cellular model for studying human pericyte biology and shows that pericyte-HK2-driven glycolysis induces tumor blood vessel abnormality by activating ROCK2-MLC2 mediated contractility." (PMID 34650057, 2021). "Mechanistically, combined proteomics and metabolic flux analysis reveals elevated hexokinase 2(HK2)-driven glycolysis in tumor pericytes, which up-regulates their ROCK2-MLC2 mediated contractility leading to impaired blood vessel supporting function." (PMID 34650057, 2021). "Overall, our results show that tumor-derived paracrine signal up-regulates pericyte-HK2-driven glycolysis to dysregulate its blood vessel supporting role by up-regulating ROCK2 mediated pathway." (PMID 34650057, 2021). "Glucose-6-phosphate dehydrogenase (G6PD) and hexokinase 2 (HK2) are key enzymes in glucose metabolism and play important roles in regulating tumor growth, metastasis, apoptosis, vasculature, and autophagy." (PMID 33718248, 2021). "In accord with its relevance in tumor settings, HK2 de novo expression or overexpression is related to poor prognosis, stage progression, metastasis and/or treatment resistance in a variety of malignancies." (PMID 33946854, 2021). "Gene expression analysis has revealed an association between higher HK2 expression and tumor aggressiveness in PDA patients, suggesting the prognostic value of HK2; however, another study highlighted an inverse correlation." (PMID 33804240, 2021). "Wild-type HK2 restored tumor growth, and K315/492R mutant HK2 promoted tumorigenesis more than wild-type HK2." (PMID 33753739, 2021). "As shown in this study, exogenous expression of HK2 activated Akt1 (p-Akt1) in cervical cancer cells, subsequently enhancing cell motility and tumor metastasis by inducing FN1, MMP2 and MMP9 expression." (PMID 34758823, 2021). "FOX transcription factor E1 (FOXE1) was recently shown to function as a tumor suppresser in CRC cases via downregulation of HK2-induced aerobic glycolysis." (PMID 34571724, 2021). "In SCC-9 cells, NR5A2 silencing downregulated the expression of MET, which is reported to be the downstream target gene of HK2 and responsible for HK2 induced tumor initiation and progression." (PMID 34277436, 2021). "Noteworthy, HK2 pharmacological inhibition or genetic downregulation suppress tumor growth or reactivate therapeutic sensitivity in a number of tumor cell models." (PMID 33946854, 2021). "Mimicking glucose molecule, [18F]FDG gets internalized into the cells via glucose transporter protein 1 (GLUT1) and metabolized intracellularly by hexokinase 2 enzyme; both molecules generally overexpressed in tumor cells." (PMID 34586539, 2021). "The tumor-specific HK2 isoform is regulated by both oncogenic and tumor suppressor microRNAs, such as miR-155 and miR-199a, respectively." (PMID 34680164, 2021). "Here, we propose that HK2 localization in MAMs of tumor cells is key in sustaining neoplastic progression, as it acts as an intersection node between metabolic and survival pathways." (PMID 33946854, 2021). "The negative regulation of HK2 by ATM was also shown by ursolic acid promoting the apoptosis of tumor cells by inhibiting HK2-mediated glycolysis, but activating ATM35." (PMID 34652890, 2021).
tumor (continued). "The pivotal role of HK2 in primary tumor growth and metastasis in PDA was demonstrated by HK2 knockdown, which led to a decrease in tumor growth both in vitro and in vivo, while its overexpression correlated with reduced overall survival in patients." (PMID 33804240, 2021). "High glycolytic rate is supported by some tumor-specific enzyme isoforms, such as hexokinase 2 (HK2) and pyruvate kinase M2 (PKM2)." (PMID 34680164, 2021). "It is important to note that HK2 expression is often upregulated in malignant tumor cells, leading to increased glycolysis." (PMID 33430318, 2021). "We also analyzed the correlation between HK2 expression and tumor stage in CC patients using the UALCAN database." (PMID 34858863, 2021). "The functional assays revealed that lncSLCC1 induced glycolysis activation and tumor growth in CRC mediated by HK2." (PMID 33602893, 2021). "The mRNA expression of Glut1, Hk2, Ldha, and Pkm2 were downregulated in the tumor tissues of BO-treated CAC mice." (PMID 34869511, 2021). "After glucose is uptaken by membrane glucose transporters (Glut) that are overexpressed in tumor cells, it is converted into glucose-6-phosphate by hexokinase II (HK2)." (PMID 33430318, 2021). "The functions of HK2 in tumor cells encompass metabolic rewiring towards aerobic glycolysis, tuning of autophagy for handling nutrient shortages and shielding from cell death stimuli." (PMID 33946854, 2021). "HK2 expression increases progressively from glottis polypus to papilloma or laryngeal squamous cell carcinoma as the clinical aggressiveness of the tumor increases." (PMID 33922558, 2021). "The biological importance of HK2 for the survival, progression, and chemoresistance of a variety of tumor types and its low abundance in normal tissues make it an attractive target for the development of anticancer therapeutics." (PMID 33187984, 2021). "In this study, we establish the role of pericyte-hexokinase 2 (HK2) driven glycolysis in remodeling tumor vasculature." (PMID 34650057, 2021). "Our present study has provided a better understanding of how enhanced HK2 expression confers aggressive tumor progression and poor prognosis in EC patients through the maintenance of mesenchymal state and increased glycolytic activity." (PMID 34174908, 2021). "According to the differential expression of HK2, the proportion of 22 tumor immune cells in ESCA was assessed by CIBERSORT research." (PMID 34708035, 2021). "In vitro migration and invasion assay, in vivo metastasis experiments were performed to detect the effective of HK2 on regulating cell motility and tumor metastasis in cervical cancer cells." (PMID 34758823, 2021). "Overall, these findings indicate that HK2 expression in tumour tissues is higher than that in adjacent healthy tissues of CRC patients and is also related to EMT and drug resistance processes." (PMID 34378321, 2021). "Conversely, HCC cells express the high-affinity HK2 to sustain tumor proliferation even at low glucose concentrations." (PMID 33920410, 2021). "Previous studies have reported that HK2 was a key target of miR‐125b and was involved in tumour progression." (PMID 34664737, 2021). "RNA-Seq was performed to explore the potential molecules that participate in HK2-mediated cell motility and tumor metastasis in cervical cancer cells." (PMID 34758823, 2021). "Hypoxia is a key feature of the tumor microenvironment and tumor infiltrated NK cells are enriched for hypoxia signatures, including expression of HK2, SLC7A5, SLC2A3, and KDM3A." (PMID 34177887, 2021). "All of these results demonstrate that HK2 promotes cell motility, suggesting that HK2 probably facilitates tumor malignant growth of metastases." (PMID 34758823, 2021). "On the other hand, HK2 is upregulated and predominantly expressed in various types of cancers, where it is required to enhance glycolysis for tumor growth and metastasis." (PMID 33187984, 2021).
tumor (continued). "As an important enzyme catalysing irreversible step of glycolytic pathway, HK2 is elevated in various cancer tissues and maintains malignant state of tumours." (PMID 34841706, 2021). "Here, the authors show that hexokinase 2- driven glycolysis activates ROCK1-MLC2 mediated contractility in pericytes leading to tumor blood vessel abnormality." (PMID 34650057, 2021). "Hexokinase 2 (HK2) depletion inhibits tumor growth and increases sensitivity to cell death inducers such as radiation and temozolomide." (PMID 34740322, 2021). "Eventually, the correlation between the expression difference of HK2 and the tumor immune cell infiltration and m6A modification of ESCA will be explored, which will help to study the potential pathogenesis of ESCA." (PMID 34708035, 2021). "Overall, our work develops a cellular model for studying pericyte biology and uncovers that pericyte-HK2-driven glycolysis induces tumor blood vessel abnormality by activating ROCK2-MLC2 mediated contractility." (PMID 34650057, 2021). "Overall, HK2 and its co-expression genes have correlation with tumor immune cell infiltration in ESCA." (PMID 34708035, 2021). "HK1 and HK2 are known as high affinity enzymes and while distribution varies in different tissue, the dysregulated expression of HK2 is marked as a tumor indicator." (PMID 33916349, 2021). "HK2 overexpression can promote the process of glycolysis of tumor cells and provide necessary energy for the proliferation and migration of tumor cells, thus promoting the occurrence and development of tumor cells." (PMID 34708035, 2021). "Overall, these data suggested that tumor-derived paracrine signal induced pericyte-HK2-driven glycolysis to dysregulate pericyte’s blood vessel supporting role by up-regulating ROCK2-MLC2 mediated contractility." (PMID 34650057, 2021). "In GBM, HK2 has been shown to be a key mediator of aerobic glycolysis and tumor growth, which is in line with our observed expression ratio of LDHA/LDHB in the IDH wild-type enriched patient cluster." (PMID 33532725, 2021). "The HK2-silenced group showed a significant reduction in tumor volume compared to the control groups." (PMID 34174908, 2021). "There are four subtypes of HK, among which the increased expression of HK2 plays an important role in promoting aerobic glycolysis in tumor cells." (PMID 33723221, 2021). "HK2 was also found to be required for tumor initiation and maintenance in mouse models of lung and breast cancer." (PMID 33187984, 2021). "Liu and colleagues have demonstrated a tumor-grade dependent increase in HK2 protein expression, whereas Mukherjee and colleagues have demonstrated a tumor-grade dependent increase in PKM2 gene expression." (PMID 35004842, 2021). "The HK2 overexpression has been shown to contribute to the enhanced glycolytic rate and tumor progression and confer resistance to apoptosis to cancer cells." (PMID 35004842, 2021). "The functions carried out by mitochondrial HK2 are required to confer tumor cells the ability to thrive and adapt even under harsh conditions of metabolic fluctuations and exposure to noxious stimuli." (PMID 33946854, 2021). "By inhibiting HK2 biological activity in tumour tissue, the energy supply to maintain tumour growth was blocked, and the proliferation of tumour cells was weakened." (PMID 31994339, 2020). "We also detected the effect of the combination of metformin and HK2 silencing on tumor cell proliferation." (PMID 32083006, 2020). "The high protein level of HK2 increases glucose/nutrient uptake and promotes macromolecular biosynthesis, which is required for sustaining of unlimited tumor cell growth." (PMID 32424132, 2020).
tumor (continued). "Hypomethylation of the promoter is responsible for the upregulation of HK2 in liver cancer and glioblastoma 41; this upregulation then enhances aerobic glycolysis and tumor proliferation." (PMID 32549751, 2020). "We also observed decreased promoter hydroxymethylation and upregulation of Hk2, which catalyzes the phosphorylation of glucose to yield glucose-6-phosphate in glycolysis and is required for tumor initiation." (PMID 33396408, 2020). "Lonidamine interferes with glycolysis in tumor cells by inhibiting hexokinase 2 (HK2), the first rate-limiting enzyme of glycolysis." (PMID 33292203, 2020). "For example, the FOXE1 TF is a critical tumor inhibitor that regulates tumor growth and glycolysis by suppressing HK2 in CRC." (PMID 32508884, 2020). "Overexpression of hexokinase 2 (HK2) plays a crucial role in the maintaining of unlimited tumor cell growth." (PMID 32424132, 2020). "Immunohistochemical staining was performed on 57 tumor tissues of ESCA patients who underwent PET/CT scan before surgery to evaluate the expression of METTL3, glucose transporter 1 (GLUT1), and hexokinase 2 (HK2) in tumor tissues and peritumoral tissues." (PMID 32626532, 2020). "Further analysis showed that this inhibition was accompanied by increased expression of the apoptosis marker, cleaved PARP, indicating that the mechanism of HK2 inhibition by lonidamine involves the induction of tumor cell apoptosis." (PMID 32083006, 2020). "Expression of HIF‐1α, GLUT1, and HK2 in 39 tumor tissues was evaluated by immunohistochemical stainning." (PMID 32533646, 2020). "In vivo, AT-I significantly inhibited tumour growth and reduced the expression of HK2, phosphorylated JAK2 and STAT3." (PMID 32273843, 2020). "Collectively, these results indicated that HOTAIR mediated the expression of HK2, which contributes to tumour growth and chemosensitivity in vivo." (PMID 32279420, 2020). "In this respect, it is noteworthy that Rg3 represses STAT3 phosphorylation in tumor cells by decreasing the hexokinase 2 level." (PMID 31936879, 2020). "In summary, we found that miR-505 acted as a key tumor suppressor miRNA through targeting oncogene HK2 in PC cells." (PMID 33520999, 2020). "It was shown that HK2 expression is enriched in many tumor cells and correlated with poorer survival rates in most neoplastic cells." (PMID 32195170, 2020). "The idea that HK2 is highly expressed in tumour cells just to ensure energy supply has begun to change." (PMID 31994339, 2020). "The Western blot of tumour tissues revealed the HOTAIR knockdown suppressed the expression of HK2 and Ki‐67, a marker of proliferation." (PMID 32279420, 2020). "While hexokinase 1 normally phosphorylates glucose on cell entry, in tumor cells hexokinase 2 has been shown to be crucial for the Warburg effect, i.e. a shift to aerobic glycolysis for ATP production, irrespective of the availability of oxygen." (PMID 32997701, 2020). "In summary, these results indicate that targeting HK2-mediated aerobic glycolysis is a promising anti-tumor strategy for OSCC treatment." (PMID 32424132, 2020). "Our findings established a previously unrecognized role for copper complex in aerobic glycolysis of tumour cells, revealing the interaction between mitochondrial HK2‐mediated mitophagy and Drp1‐regulated mitochondrial fission." (PMID 31994339, 2020). "In a study of C3H/He mice implanted with MH134 mouse HCC cells and successively treated with 3-BrPA, 3-bromopyruvate (3-BrPA), a HK2 inhibitor, mean tumor volume was shown to be significantly reduced." (PMID 33182674, 2020). "We revealed that suppression of Akt-c-Myc-HK2 axis played a critical role in Tan IIA-induced anti-tumor activity." (PMID 32424132, 2020). "In vivo experiments using xenograft models revealed that stable over-expression of MZF1 promoted the tumorigenecity of SH-SY5Y cells, as displayed by increase in tumor growth, tumor weight, Ki-67 proliferative index, and elevated levels of HK2 and PGK1." (PMID 32042322, 2020).
tumor (continued). "We suggest that a key intermediate must exist between HDACs and HK2, mediating the regulation of HK2 expression levels and tumour metabolism by HDAC4 and HDAC5." (PMID 32519437, 2020). "In accordance with the suppression of tumor glycolysis, the expression of HK2 which is the key enzymes of glucose metabolism was markedly decreased in a dose-dependent manner." (PMID 33425771, 2020). "HK2 depletion or inhibition decreased the glycolysis and tumor growth via activating AMPK signaling pathway, which downregulated mTORC1 activity." (PMID 32083006, 2020). "HK2 depletion or metformin alone also significantly inhibited colony formation; importantly, the combination of metformin and HK2 depletion decreased tumor growth much more substantially than either treatment alone." (PMID 32083006, 2020). "The human HK2 gene was evaluated by real-time PCR and normalized to mouse 18S to reflect the amount of circulating tumour cells in the peripheral blood of mice." (PMID 32093760, 2020). "3-BP is an alkylating agent that inhibits HK2 and selectively kills cancer cells, and is capable of suppressing tumor cell glycolytic capacity by abolishing mitochondrial-bound HK2 activity." (PMID 31948035, 2020). "In our study, we showed that the abnormal expression of HK2 in GBM contributes the tumour cells proliferation and resistance to TMZ‐induced apoptosis." (PMID 32279420, 2020). "There was no such difference in total NSCLC patients (tumor n = 1,017, normal n = 110), and normal tissues (n = 59) showed higher HK2 expression than tumor tissues (n = 515) from ADC patients." (PMID 32083006, 2020). "IHC results indicated that HK2 expression was remarkably down‐regulated by SNHG1 knockdown in xenograft tumours formed from a stable EJ cell line." (PMID 32885590, 2020). "FOXE1 functions as a critical tumor suppressor in regulating tumor growth and glycolysis via suppressing HK2 in CRC." (PMID 31918722, 2020). "In sum, our findings suggest that the UCA1/miR-203/HK2 axis contributes to EC development by reprogramming tumor glucose metabolism, providing new insight into the management of EC patients." (PMID 33204264, 2020). "The mean METTL3, GLUT1, HK2 immunohistochemical staining score in the tumor tissues was significantly higher than that in the peritumoral tissues (p < 0.001)." (PMID 32626532, 2020). "In fact, HK2 silencing and the treatment with complex I inhibitor, metformin, had a synergistic effect on subcutaneous tumor growth in vivo." (PMID 33182674, 2020). "The role of HK2 in regulating tumor metastasis in vivo was further defined in a previously established primary and metastatic xenografic tumor model." (PMID 32195170, 2020). "HK-2 overexpression is positively related to the high level of tumor glycolysis and the low overall survival of tumor patients." (PMID 32489324, 2020). "First of all, our results have shown substantial differences between GSC lines not only in protein expression but also in mRNA concerning HIF-1 and other important markers such as VEGF or HK2, confirming the heterogeneity of this kind of tumor." (PMID 32290386, 2020). "With a natural product screening, we identified Tanshinone IIA (Tan IIA) as a potential anti-tumor compound for OSCC through suppressing HK2-mediated glycolysis." (PMID 32424132, 2020). "On the other hand, miR-652 directly represses the expression of HOXA9 and leads to the activation of the HIF-1 signaling pathway promoting tumor proliferation and migration in UM through HK2, a mechanism that was mentioned in the previous section." (PMID 33053887, 2020). "In this study, we found that the GBM patients received TMZ treatment with tumour recurrence has higher HK2 expression." (PMID 32279420, 2020). "We then evaluated the effect of HK2/HKDC1 expression on tumor growth through thymidine incorporation and [3H]-deoxyglucose uptake." (PMID 32203147, 2020).